MBP (myelin basic protein)
Diseases named in the same sentence as MBP in open-access papers (continued):
Sharing a sentence is not in itself a finding about the gene and the disease.
leukodystrophies (5 papers, 2013 to 2021). "The data presented are of potential clinical relevance as the human orthologs of the Zfp191 and MBP genes reside on a region of Chromosome 18 that is deleted in childhood leukodystrophies." (PMID 27683878, 2016). "OL defects in specific leukodystrophies may be due to defects in OL differentiation, in altered MBP production, or impairment of the mechanism for myelin deposition." (PMID 33815061, 2021). "Developmental myelinopathies exist on a clinical spectrum, but MBP is not included on leukodystrophy or CMT gene panels." (PMID 31788257, 2019).
neuromyelitis optica (5 papers, 2015 to 2025). A rare inflammatory disease of the central nervous system characterized mainly by attacks of uni- or bilateral optic neuritis (ON) and acute myelitis. "Furthermore, previous studies have indicated that CSF MBP levels are elevated in anti-MOG antibody-positive patients with neuromyelitis optica spectrum disorder (NMOSD), transverse myelitis, and acute disseminated encephalomyelitis (ADEM)." (PMID 33391163, 2020). "Myelin basic protein (MBP) and serum neuromyelitis optica (NMO) antibodies were negative." (PMID 26236276, 2015).
oligodendroglioma (5 papers, 2013 to 2025). A well-differentiated (WHO grade II), diffusely infiltrating neuroglial tumor, typically located in the cerebral hemispheres. "MBP is downregulated in oligodendrogliomas, with expression levels showing high variability across different LGG cell types." (PMID 41007824, 2025). "In other studies, MBP was highly expressed in oligodendroglioma while minimally expressed in GBM." (PMID 37377888, 2023). "Mature oligodendrocyte markers, such as myelin basic protein (MBP) and proteolipid protein (PLP), however, are not expressed at detectable levels in oligodendrogliomas." (PMID 37274223, 2023).
vitamin B12 deficiency (5 papers, 2013 to 2022). A disease characterized by low serum levels of vitamin B12, either inherited or acquired. "Low levels of vitamin B12 or folic acid can increase Hcy levels, and vitamin B12 deficiency can cause myelin damage due to inadequate methylation of myelin basic protein." (PMID 35911688, 2022). "Vitamin B12 deficiency interferes with production of choline and choline-containing phospholipids, oligodendrocyte function, and myelin basic protein methylation." (PMID 23840983, 2013). "Elevated plasma homocysteine is suggestive of impaired transmethylation due to folate or vitamin B12 deficiency, which may impact myelin structure and remyelination due to decreased methylation of myelin basic protein." (PMID 32575774, 2020). "In line with these manifestations, vitamin B12 deficiency may serve as a metabolic factor for imperfect methylation of a major component of CNS myelin which is myelin basic protein (MBP)." (PMID 24800049, 2014).
acute disseminated encephalomyelitis (4 papers, 2020 to 2025). Acute disseminated encephalomyelitis (ADEM) is a demyelinating disorder of the central nervous system. "Nonetheless, MBP provides evidence of active myelin breakdown, and high MBP levels in CSF correlate with severe attacks or acute disseminated encephalomyelitis." (PMID 40361996, 2025). "The clinical course and CSF analysis showing elevated myelin basic protein levels (157 pg/mL, reference value below 102.0 pg/mL) confirmed acute disseminated encephalomyelitis (ADEM)." (PMID 40018425, 2025). "The immunogenic/antigenic role of myelin basic protein may account for the over-/misinterpretation of the EAE model that has led to the widespread correlation of this model with MS rather than acute disseminated encephalomyelitis (ADEM)." (PMID 33117365, 2020).
allergic disease (4 papers, 2016 to 2025). An immune response that occurs following re-exposure to an innocuous antigen, and that requires the presence of existing antibodies against that antigen. "Staining ECP (rather than MBP or EPO) as a markers of intensity of eosinophilic inflammation of the airways in allergic diseases, allowed us to compare our results with other DE controlled exposure studies." (PMID 26758251, 2016).
Ataxia (4 papers, 2014 to 2022). Ataxia refers to impaired coordination of voluntary muscle movement. "Shiverer mice have a spontaneous deletion of multiple exons in the gene encoding myelin basic protein (MBP), resulting in pronounced ataxia by 2–3 weeks of age, as well as the onset of fatal seizures by ~8–14 weeks." (PMID 30804753, 2019). "Titers of anti-NF, but not GFAP or MBP, NAb significantly correlated with changes in gait considered indicative of ataxia in OPIDP, decrease in stride length, and increase in width." (PMID 25045531, 2014). "The lack of associations with GFAP and MBP is consistent with the primary targeting of neurons in OPIDP, although the earlier study did show associations with anti-MBP, secondary myelin involvement, and scored clinical ataxia." (PMID 25045531, 2014). "Clinical disease activity status, however, improvement upon IVIg-treatment, or clinical features such as tremor and ataxia were independent of T cell reaction specific to NF155, NF186, P0 180–199, or MBP 82–100." (PMID 29615965, 2018).
glioblastoma (4 papers, 2012 to 2023). The most malignant astrocytic tumor (WHO grade IV). "MBP has been viewed as a potential biomarker for various types of tumors including glioblastoma in cerebrospinal fluids." (PMID 37377888, 2023).
Immunodeficiency (4 papers, 2016 to 2025). Failure of the immune system to protect the body adequately from infection, due to the absence or insufficiency of some component process or substance. "In addition, the expression of MBP in enteric glial cells and 3A6/DR2a Tg animals’ partial immunodeficiency stemming from allelic exclusion, which is caused by the expression of a transgenic TCR, may promote the development of colitogenic T cells in 3A6/DR2a Tg mice." (PMID 36341389, 2022).
leprosy (4 papers, 2018 to 2022). Leprosy is a chronic infectious disease affecting primarily the skin and peripheral nervous system. "The T cell epitopes were found to be associated with high CMI for keratin and MBP in the T1R group of leprosy patients." (PMID 34952925, 2021). "Our group recently demonstrated a rise in both T and B cell responses to keratin and myelin basic protein in all types of leprosy patients and their associations in type 1 reaction (T1R) group of leprosy." (PMID 29666623, 2018). "High levels of anti-MBP antibodies in leprosy patients across the spectrum and cross-reactivity between epitopes of human myelin A1 with 50S ribosomal L2 and lysyl tRNA synthetase of M. leprae have been reported." (PMID 36560940, 2022). "The presence of autoantibodies like rheumatoid factor, antinuclear factor, and antibodies to host collagen, keratin, actin, myosin, endothelial cells, and myelin basic protein (MBP) has been earlier reported in leprosy patients." (PMID 36560940, 2022). "Whilst most of the genes overlap between the two comparisons, some genes discriminate leprosy patients from HHC exclusively (MBP, MSR1, TLR1, CAMTA, CXCL13 and TFGB)." (PMID 31784594, 2019). "Similarly, we observed a higher level of antibodies in leprosy patients when compared to HC for two mimicking B cell epitopes of MBP (similar to lysyl tRNA synthetase) MBPLMB1 and MBPLMB2." (PMID 34952925, 2021). "Presence of autoantibodies like, rheumatoid factor, anti-nuclear factor and antibodies to host, collagen, keratin, myelin basic protein (MBP) and myosin, have been earlier reported in leprosy patients." (PMID 34952925, 2021). "When comparing leprosy patients to HHC, 16 genes showed significantly different expression for leprosy patients (increased: FCGR1A, IL6, IL15, LRKK2, MBP, MSR1, PACRGv1, TLR1, TLR4; decreased: CAMTA, CD3E, CTLA4, CXCL13, GATA3, LAG3, TFGB)." (PMID 31784594, 2019). "In the case of two mimicking B cell epitopes of Myelin Basic Protein (similar to 50S ribosomal protein of M. leprae) MBP50SB1 and MBP50SB2, we observed significantly higher antibody levels in leprosy patients when compared to HC (p < 0.05 and p = ns, respectively)." (PMID 34952925, 2021). "Importantly, whilst most of these genes were also differently expressed in leprosy patients compared to EC, MBP, MSR1, TLR1, CAMTA, CXCL13 and TFGB were differentially expressed in leprosy patients exclusively when compared to HHC." (PMID 31784594, 2019).
lung cancer (4 papers, 2015 to 2025). A malignant neoplasm involving the lung. "After brain metastasis of lung cancer, damage to the CNS is caused by invasion and compression of cancerous tissues, which in turn causes an increase in the level of peripheral blood MBP." (PMID 40361513, 2025). "The aim of the present study was to determine the association between the expression of myelin basic protein in the serum and the metastasis of lung cancer to the brain." (PMID 25667676, 2015). "The aim of the study was to determine the association between the expression of myelin basic protein and brain metastasis of lung cancer, in order to help physicians establish an earlier diagnosis." (PMID 25667676, 2015). "It is suggested that serum MBP has high specificity in the diagnosis of brain metastasis of lung cancer, and MBP can be used as a serological marker for early diagnosis of brain metastasis of lung cancer." (PMID 40361513, 2025). "In the lung cancer with brain metastasis group, the correlation between the size of brain metastasis and the level of myelin basic protein was analyzed, and the R2 value was determined to be 0.0242." (PMID 25667676, 2015). "In the present study, a clinical investigation was performed to analyze the correlation between the expression of myelin basic protein in the serum and brain metastasis from lung cancer." (PMID 25667676, 2015). "Despite the limitations, the results of the present study demonstrated a statistically significant correlation between the expression of myelin basic protein in the serum and the metastasis of lung cancer to the brain." (PMID 25667676, 2015). "The human brain myelin basic protein (MBP) is also distributed in the nervous system and extensively in other tissues, where it can be detected in many types of tumor cells, such as neuroglioma, lung cancer, and breast cancer." (PMID 38137332, 2023). "Myelin basic protein may thus prove useful in the early diagnosis of brain metastases in lung cancer patients." (PMID 25667676, 2015). "Therefore, the results demonstrated a statistically significant correlation between the expression of myelin basic protein in the serum and the metastasis of lung cancer to the brain." (PMID 25667676, 2015). "The observations of the present study indicated that the measurement of myelin basic protein may aid physicians in diagnosing the metastasis of lung cancer to the brain." (PMID 25667676, 2015). "Thus suggesting that myelin basic protein may prove useful in the early diagnosis of brain metastases in patients with lung cancer." (PMID 25667676, 2015). "Therefore, in the present study, the concentration of myelin basic protein was hypothesized to increase in the serum of lung cancer patients with a brain metastasis." (PMID 25667676, 2015). "Therefore, brain metastasis may be identified and treated earlier using myelin basic protein as a marker, which may considerably improve the efficacy of treatment and the quality of life of lung cancer patients." (PMID 25667676, 2015). "In the current study, the expression levels of myelin basic protein were analyzed in 68 lung cancer patients with or without brain metastasis, treated at the Department of Respiratory Medicine of the People’s Hospital of Rizhao (Rizhao, China)." (PMID 25667676, 2015).
psychosis (4 papers, 2016 to 2022). "In our study, both antipsychotic-naive SCZ and BD patients exhibited increased MBP expression levels (most likely Golli isoforms) compared with healthy controls, suggesting that this gene might be associated to psychosis per se, as both patient groups exhibited psychotic symptoms." (PMID 27701407, 2016). "The Ota 2015 study showed an increase of MBP gene expression in the peripheral blood of antipsychotic-naïve patients with first-episode psychosis." (PMID 34025476, 2021). "Particularly, myelin basic protein (MBP) and NudE neurodevelopment protein 1 like 1 (NDEL1) genes were upregulated in the first episode of psychosis, as compared with other groups, and were possibly related to the first molecular signs of SZ." (PMID 33020462, 2020). "In addition, MBP and NDEL1 expression levels were higher in both SCZ and BD patients than in healthy controls, indicating that these genes may be related to psychosis per se (independently of diagnosis)." (PMID 27701407, 2016). "Furthermore, MBP and NDEL1 expression levels were higher in SCZ and BD patients than in healthy controls, indicating that these genes are psychosis related (independent of diagnosis)." (PMID 27701407, 2016).
Sepsis (4 papers, 2020 to 2025). Sepsis is defined as life-threatening organ dysfunction caused by a dysregulated host response to infection. "IHC results revealed that in a mouse model of sepsis, the expression level of MBP in the cerebral white matter region was significantly decreased, with its positive staining intensity notably weakened, which suggests myelin sheath loss or damage." (PMID 41584453, 2025). "Our findings reveal that glycine may improve the destruction of MBP protein in septic mouse brain tissue, implying that glycine can reduce myelin reduction during sepsis-induced WMI." (PMID 41584453, 2025). "First, in our study, the reduction in the expression of MBP in neonatal sepsis survivors might have already been compensated for by endogenous mechanisms." (PMID 33339379, 2020). "The sepsis group had decreased ALB and MBP values and higher HCT-ALB values and SOFA scores than in the non-sepsis group." (PMID 41294166, 2025). "In contrast, β-actin promoter-driven SRG3 overexpression attenuated the severity of MBP-induced EAE and reduced the clinical symptoms of LPS/D-GalN-induced sepsis via alternative macrophage activation." (PMID 39519233, 2024).
AIDS (3 papers, 2018 to 2022). A syndrome resulting from the acquired deficiency of cellular immunity caused by the human immunodeficiency virus (HIV). "Among autoAbs in HIV/AIDS, Abs against DNA, histones, and MBP should be discussed separately, especially those that bind these substrates and catalyze their specific hydrolysis." (PMID 35335016, 2022). "It has been shown that IgG and/or IgM of patients with AIDS hydrolyze not only autoantigens as DNA, MBP, histones, but also viral enzymes HIV integrase and HIV reverse transcriptase and corresponding peptides." (PMID 35335016, 2022). "It is challenging to explain binding polyspecificity and catalytic polyreactivity of natural anti-MBP and antihistone Abs in HIV/AIDS only by the similarity of these antigens." (PMID 35335016, 2022).
amyloid (3 papers, 2018 to 2025). "Axonal/myelin injury results in formation of myelin aggregates, and degraded MBP binds AβPP and Aβ peptides, and along with LPS and other molecules leads to the formation of amyloid plaques." (PMID 29520228, 2018). "However, the absence of MBP decreases the accumulation of Aβ1–42 in transgenic AD mice, and essentially eliminate amyloid plaques." (PMID 29520228, 2018). "However, the MBP-/- mice have virtually no amyloid plaques which we propose is due to the fact that plaque formation may require aggregation of MBP and cholesterol with Abeta (see next section)." (PMID 36845656, 2023).
amyotrophic lateral sclerosis (3 papers, 2019 to 2022). Amyotrophic lateral sclerosis (ALS) is a neurodegenerative disease characterized by progressive muscular paralysis reflecting degeneration of motor neurons in the primary motor cortex, corticospinal tracts, brainstem and spinal cord. "Interestingly, the disease mechanisms of amyotrophic lateral sclerosis (ALS) involve mRNA transport and liquid–liquid phase separation, which both are attributes related to MBP in oligodendrocytes." (PMID 34889995, 2022).
autism spectrum disorder (3 papers, 2020 to 2022). A spectrum of developmental disorders that includes autism, and Asperger syndrome. "Such a situation has been reported for BTBR mice strain, an autism spectrum disorder mouse model, in which neonatal frontal brain myelination is increased, associated with elevated levels of MBP." (PMID 36359880, 2022).
Brain atrophy (3 papers, 2009 to 2024). Partial or complete wasting (loss) of brain tissue that was once present. "It ameliorates brain atrophy and ventricle enlargement while limiting tau hyperphosphorylation and neuronal and myelin basic protein loss." (PMID 38231413, 2024). "Higher concentrations of fractalkine were, however, associated with higher titers of anti-MBP antibodies (r = 0.413, P = 0.021) and increased brain atrophy (r = 0.879, P = 0.004)." (PMID 20142990, 2009).
central nervous system demyelinating disease (3 papers, 2009 to 2025). "Myelin basic protein, an important antigen for T cells and CNS demyelinating disease, was reported to have a region with a structural similarity to human papillomavirus peptides." (PMID 34540856, 2021). "While MBP normally is not detectable in CSF, following an acute relapse of the demyelinating disease multiple sclerosis (MS), CSF MBP levels rise transiently in the range of ng/ml." (PMID 40061215, 2025).
cerebral infarction (3 papers, 2016 to 2025). An ischemic condition of the brain, producing a persistent focal neurological deficit in the area of distribution of the cerebral arteries. "Consistent with previous findings, BM-MSC improved poststroke survival, enhanced neurological, reduced cerebral infarct volume, preserved white matter integrity (MBP staining), and mitigated inflammatory cell infiltration." (PMID 41241718, 2025).
endometriosis (3 papers, 2021 to 2024). The growth of functional endometrial tissue in anatomic sites outside the uterine body. "MBP is another metabolite of DnBP that was consistently higher among women with endometriosis in our study." (PMID 34227050, 2021). "We observed association between endometriosis and increased urinary levels of MBP/MnBP, MEOHP, and MEHHP, but not for others." (PMID 34227050, 2021). "Similarly, in a different cross-sectional study, a nonsignificant association between MBP and endometriosis was also found." (PMID 39200395, 2024). "In the urine, MEHP and ∑DEHP concentrations were significantly increased, while the metabolites MEP, MiBP, MBP, MEOHP, MEHHP, and MECPP had lower concentrations in the endometriosis group." (PMID 39200395, 2024). "MBP, MEOHP, MEHHP, MEHP, and MMP exposure tended to increase the risk of endometriosis, but this effect was not statistically significant." (PMID 34227050, 2021). "In contrast, urine concentrations of MBP (SMD 0.20, 95% CI 0.07–0.32; p <0.05), MEOHP (SMD 0.29, 95% CI 0.04–0.53; p <0.05), and MEHHP (SMD 0.34, 95% CI 0.07–0.61; p <0.05) were significantly higher in the endometriosis group compared to the control group." (PMID 34227050, 2021). "The present meta-analysis found that women with endometriosis had higher urinary levels of MBP, MEOHP, and MEHHP and higher blood levels of BBP, DEHP, DnBP, and MEHP than women without endometriosis." (PMID 34227050, 2021).
eosinophilia (3 papers, 2017 to 2023). "Nippostrongylus brasiliensis infection takes about 7 days to induce eosinophilia, so IL-5 appeared well after the activation of T cells to MBP." (PMID 29163523, 2017). "After demonstrating MBP, CCL5 and CCL11 in tissues of affected organs and presence of eosinophilia, we next evaluated levels of these and other eosinophilic granules and chemokines in sera." (PMID 28489854, 2017).